CD4 (CD4 molecule)
Diseases named in the same sentence as CD4 in open-access papers (continued):
Sharing a sentence is not in itself a finding about the gene and the disease.
Opportunistic infection (continued). "Moreover, HIV-infected patients who maintain viral suppression and had CD4+ T-cells ≥300 cells/μL are unlikely to experience counts <200 cells/μL (threshold for opportunistic infection risk), suggesting that routine CD4+ T-cells monitoring may be unnecessary in some scenarios." (PMID 31447862, 2019). "In addition to opportunistic infections, most MDR-TB and HIV co-infected patients included in retained studies, reported low CD4 cells < 100 cells/mm3, being severely underweight and having chest cavity lesions at baseline." (PMID 31420021, 2019). "Although CD4 monitoring remains essential for the detection and management of HIV-related opportunistic infections such as Cryptococcus, signatories of a 2017 advanced HIV position statement claim donor support for CD4 testing at the primary care level has decreased in recent years." (PMID 30892272, 2019). "CD4 enumeration has previously been used in resource-limited settings to determine treatment eligibility of HIV-positive patients and for routine monitoring to identify treatment failure and opportunistic infections." (PMID 31276477, 2019). "Although we did not monitor changes in CD4+ cell counts, no serious opportunistic infections were observed after chemotherapy." (PMID 30926889, 2019). "WHO currently recommends antiretroviral therapy (ART) for all HIV positive patient regardless of CD4 counts, but in many resource limited settings, CD4 counts are used in the management of HIV-positive patients to evaluate immune status and to direct treatments of suspected opportunistic infection." (PMID 30138398, 2018). "Women with lower CD4 count might have advanced WHO clinical stage, they might have been diagnosed as HIV positive a long time ago and might have frequently developed opportunistic infections." (PMID 29879969, 2018). "Genetic variation in CXCR2, a receptor for IL-8, has not been significantly associated with HIV-1 VL or CD4 count, although the CXCR2 (+1208) T/C polymorphism is linked to the incidence of opportunistic infections among HIV patients in South Africa." (PMID 30534128, 2018). "Antiretroviral therapy increases the length and quality of life and productivity of patients by improving survival and decreasing the incidence of opportunistic infections in PLWHA through the reduction of circulating viremia and increasing the level of CD4+ cells." (PMID 30344850, 2018). "Unlike other opportunistic infections which occur at CD4+ counts below 200/mm3, TB can crop up at any stage of the disease." (PMID 30915136, 2018). "IRIS was more common in participants initiating ART at older ages (p = 0.005), with lower CD4 counts (p < 0.001) or with pre-existing TB (p = 0.007); IRIS was less common in those initiating ART with enhanced prophylaxis against opportunistic infections (p = 0.001)." (PMID 30513108, 2018). "Stable patients (aged ≥18 years, on first‐line ART ≥12 months, CD4 count ≥300 cells/mL3, without opportunistic infections, not pregnant/breastfeeding) were eligible for SMCC, with three‐monthly drug refills from community health workers." (PMID 30450699, 2018). "In the long term, early HIV diagnosis and initiation of HAART irrespective of CD4 count will reduce the frequency of the opportunistic infections, hospitalizations, and mortality." (PMID 28819470, 2017). "Therefore, in addition to immunodeficiency due to CD4+ T cell depletion, it is possible to speculate that possible elimination or impairment of IL-17-producing cells in the oral mucosa in the course of HIV infection might be associated with susceptibility to OPC and other opportunistic infections." (PMID 28326084, 2017). "Mortality is associated to advanced disease stages, severity of immunologic compromise (low CD4 count), presence of opportunistic infections, and lack of resources for care." (PMID 29132400, 2017).
Opportunistic infection (continued). "In this population, neither opportunistic infections nor adverse events were increased, and CD4+ T cell counts did not decrease significantly during therapy." (PMID 28638104, 2017). "Thus, the BD FACSPrestoTM is a potential addition to the CD4 testing network to both assess ART eligibility and support opportunistic infection monitoring." (PMID 28448581, 2017). "The following criteria were used for patient enrollment: (a) detection of anti-HIV antibody; (b) CD4 counts ≥ 350 cell/μL at the time of enrollment; and (c) absence of opportunistic infections at the time of enrollment." (PMID 28050553, 2016). "In clinical practice, CD4 cell counts are used to measure the degree of HIV-induced immune suppression which guides decisions on antiretroviral therapy (ART) and the need for prophylaxis against opportunistic infections." (PMID 27417903, 2016). "Viral hepatitis (AOR = 6.02; 95% CI = 1.87–19.39), opportunistic infections (AOR = 2.91; 95% CI = 1.04–8.19), current CD4 count <200 cells/mm3 (AOR = 2.16; 95% CI = 1.06–4.39), and male sex (AOR = 1.83; 95% CI = 1.001–3.33) were associated with elevated ALT and/or AST." (PMID 27493798, 2016). "Furthermore, CD4 testing remains beneficial for HIV disease and opportunistic infection management of patients on ART." (PMID 27175484, 2016). "Prevention and control of TB and other opportunistic infections, promotion of ART initiation at higher CD4 level, and better functional status, improving drug adherence are important interventions to reduce treatment failure among ART clients in Southeastern Ethiopia." (PMID 27716827, 2016). "Opportunistic infections at the start of ART and during the treatment period could affect the CD4 count change over time." (PMID 27475982, 2016). "In both of our patients, the regulatory CD4+CD25+ T cell subset was significantly increased when opportunistic infections occurred, although we did not examine Foxp3 expression." (PMID 26693362, 2015). "Further, in the many areas without access to viral load testing, CD4+ counts are often used to assess the success of cART, and the decision to commence or change opportunistic infection (OI) prophylaxis invariably requires CD4+ counts." (PMID 26110761, 2015). "It presents a cost profile differentiated by initiation of treatment at different CD4 cell count levels; time on treatment; cost components (e.g., drug and personnel costs) for HIV care and opportunistic infections (OIs); and finally patient costs of seeking and undergoing care." (PMID 26424195, 2015). "CD4+ T-cell counts of at least 200/mm3 in last 6 months prior to transplant, with no previous serious opportunistic infections." (PMID 25725240, 2015). "We assert that COC use and condom use do not cause HAART use as in this setting prescription of HAART is based on CD4+ cell count and presence of opportunistic infections, neither of which is likely to be affected by COC or condom use." (PMID 24979709, 2014). "Interested candidates were screened to ensure they were more than six months on ART, had a CD4 count >200 cells/mm3, and no active opportunistic infections." (PMID 24735550, 2014). "Inexpensive interventions to prevent opportunistic infections in resource-poor settings can improve clinical outcomes in PLHIV and may help reduce viral loads and maintain CD4+ cell counts (CD4 counts)." (PMID 25233345, 2014). "In contrast to other HIV-associated opportunistic infections, TB can occur in HIV-infected patients at any level of immunodeficiency, regardless of CD4+ T cell counts." (PMID 25160905, 2014). "He then had good viral load suppression with anti-retroviral therapy, but his maximum CD4 count was only 120 cells/mm3 (baseline 55 cells/mm3 at diagnosis); he had not suffered opportunistic infections." (PMID 26530344, 2014).
Opportunistic infection (continued). "Herein, we focused on patients surviving chronic HIV infection for at least 15 years with a long history of suppressed viremia under antiretroviral therapy in the majority, high CD4 median level, and no opportunistic infection at time of analysis." (PMID 23678991, 2013). "Our patients had no opportunistic infections and only one of them had CD4 count of less than 200/mm3." (PMID 24570775, 2013). "Unlike other opportunistic infections, HZ occurs at a wide range of CD4 counts in HIV-positive subjects." (PMID 23937603, 2013). "Secondly, individuals have been identified with low levels of CD4 without HIV infection, both associated with opportunistic infections and also when asymptomatic." (PMID 23527284, 2013). "For instance, our patient #2 had a CD4 count of 703/μl with no history of opportunistic infection; he was started on HAART prior to initiation of chemotherapy because of the risks for further immunosuppression and bone marrow suppression." (PMID 24252328, 2013). "Multiple studies have reported promising results of HAART-treated HIV-infected patients with maximally suppressed viral loads, stable CD4 counts, and no significant increase in opportunistic infections after OLT." (PMID 22900154, 2012). "LTNP were defined as: HIV-1+ for >7 years; ART-naïve; no history of opportunistic infection and normal, stable CD4+ T-cell counts." (PMID 22363409, 2012). "Unlike other opportunistic infections which occur at CD4+ lymphocyte count below 200/mm3, active TB occurs throughout the course of HIV disease." (PMID 22738361, 2012). "Only a few treatment changes occurred during pregnancy (n: 7, 10.3%), because of drug intolerance (n:2) and lack of therapeutic response (n: 5, defined by a CD4 count drop >25%, a viral load increase >30%, or development of opportunistic infections)." (PMID 22558455, 2012). "LTNP are HIV-1+ patients who maintain stable CD4+ T-cell counts, with no history of opportunistic infection or antiretroviral therapy (ART)." (PMID 22363409, 2012). "Surprisingly for the optimal and continuous treatment the CD4+ cell count are not related to the outcome of the opportunistic infection (p-value 0.29 and 5.1*10−2)." (PMID 22558348, 2012). "Above 500 CD4 cells/μl it would be highlyunusual for there to be opportunistic infections and the most recent NIH guidelinesdo not recommend treating above this level." (PMID 21544209, 2011). "No clinically significant differences in opportunistic infections, adverse events, adherence or viral resistance were noted; after randomization, long-term CD4 rise was observed only in the cART arm." (PMID 21738668, 2011). "Unlike other opportunistic infections there are some reports of VL relapse in patients with a CD4+ count greater than 200 cell/mL in Ethiopia, and rarely in Europe." (PMID 21666786, 2011). "These included the baseline (i.e. pre-ART) CD4 count category, the current CD4 count category, baseline and current viral load categories, time on ART, being on a first or second line ARV regimen, opportunistic infections or WHO staging; and adverse events on ART." (PMID 20594369, 2010). "Follow-up of a cohort of 41 HIV-1+ individuals originally defined as “LTNP” in 1996 and identified according to clinical criteria: CD4 count, length of infection and lack of opportunistic infection, was undertaken." (PMID 19434236, 2009). "In HIV-infected ALA patients, CD4 counts varied greatly from 14 to 798/μL, suggesting that ALA is not caused by an opportunistic infection." (PMID 18416821, 2008). "Overall, 58% (14/24) of HIV-infected patients had a CD4+ count > 200 cells/μL and 82.1% (23/28) had no concurrent opportunistic infection or other evidence of HIV infection." (PMID 18416821, 2008). "It is therefore arguable that in a CD4+-lymphopenic setting, preservation of CD8+ effector function may be essential in the prevention of opportunistic infections." (PMID 18974880, 2008).
Opportunistic infection (continued). "When only analysing participants with confirmatory CD4 testing ≤200 cells/μl, time to ART was shorter among clinics assigned to the Visitect CD4 platform; however, there were no longer differences in severe adverse events, hospitalizations or opportunistic infections." (PMID 41566892, 2026). "In people with HIV, anemia may also arise from nutritional deficiencies, chronic inflammation, ART-related marrow suppression, or opportunistic infections, which could influence hemoglobin, hematocrit, and RBC levels independently of CD4-defined immunosuppression." (PMID 41374357, 2025). "This might be due to, poor adherence could result in reduced viral load suppression and decreased CD4 cell count, which leads to uncontrolled HIV replication, and the patient’s immune system becomes compromised and can’t fight off opportunistic infections, which ends up in mortality." (PMID 39761319, 2025). "Additionally, individuals with HIV RNA levels above 5,000 copies/mL, CD4+ T-cell counts below 350 cells/μL, CD8 counts below 500 cells/μL, and those without opportunistic infections demonstrated significant reductions in CD4+ T-cell recovery probability." (PMID 40421011, 2025). "Clinical factors associated with higher VF rates were ambulatory status (44.7%, p < .001), low CD4 count (35.1%, p < .001), low haemoglobin (52.2%, p < .001), advanced HIV stage III/IV (44.2%, p < .001), HIV/TB co-infection (24.3%, p < .001), and other opportunistic infections (20.5%, p = .008)." (PMID 40219653, 2025). "Consistent with the literature, we substantiated that liver transplantation is feasible in this patient population; indeed, postoperative HAART therapy can suppress the viral load, stabilize CD4 T-cell count, and lead to no significant increase in opportunistic infections." (PMID 38589801, 2024). "In addition, none of the participants in our cohort of PWH presented opportunistic infections, which proved that their immune system was competent, and consequently, that their CD4+ T cells were not dysfunctional." (PMID 38812512, 2024). "Finally, concomitant use of the antibiotic cotrimoxazole to prevent opportunistic infections with ART regardless of CD4 + T cell count is more common in SSA compared to developed countries." (PMID 38310301, 2024). "In total, 28.81% of MSM, 67.65% of HTXs, and 60% of IDUs were diagnosed as late presenters (LPs), indicating individuals diagnosed with either a CD4+ T cell count below 350 cells/μL or diagnosed with an opportunistic infection, regardless of the CD4+ T cell count at the time of diagnosis." (PMID 39339921, 2024). "Independent predictors for CD4 cell count were age, weight, baseline CD4 cell count, cell phone ownership, visit time, marital status, residence, and level of disclosure of the disease to family members, household income, WHO clinical stage, ART adherence,opportunistic infections." (PMID 38042846, 2023). "In this study, the severity of HIV infection, measured using the CD4+ cell count at baseline and transplantation, CD4+ T-cell count nadir, and pre-LT opportunistic infections, did not affect graft and patient survival, validating the HIV-related eligibility criteria." (PMID 37895356, 2023). "However, in HIV-infected patients, serum CD4+ T lymphocytes counts mainly reflected a probability of various opportunistic infections, which is not a good predictor of cancer survival prognosis." (PMID 36923659, 2023). "Not all the PWH present opportunistic infections at the same levels of circulating CD4+ T-cells." (PMID 36813761, 2023). "Third, we suspect that RCC has an association with HIV-induced immunodeficiency, but patients with low CD4 T cell counts tend to be diagnosed with ADC and have a worse prognosis; thus, they may die because of ADCs and opportunistic infections at a younger age before they develop RCC." (PMID 35433425, 2022).
Opportunistic infection (continued). "For example, data on CD4 measurements, viral load, opportunistic infections, weight, and height were more than 25% missing and could not be assessed in the analysis." (PMID 36962289, 2022). "Furthermore, comorbid medical diseases, recent CD4 counts, and opportunistic infections were not statistically significant factors in the multivariate logistic regression for co-occurring anxiety and depression." (PMID 35558427, 2022). "Moreover, it has never been reported as the presenting manifestation of HIV and HBV co-infection, even more so when the patient had a normal CD4 count and no demonstrable opportunistic infections." (PMID 36382206, 2022). "His CD4 count was normal, and he had no demonstrable opportunistic infections." (PMID 36382206, 2022). "CRP was higher among cART-treated HIV-infected than age-matched healthy HIV-negative adults from the same communities; despite more than twelve years of suppressive cART, restoration of CD4 counts to at least 500 cells/μl and no opportunistic infections within the 6 months preceding our study." (PMID 34445953, 2021). "Preoperative CD4 T cells, presence or absence of opportunistic infection, and organ dysfunction were used to identify whether there was SSI in the patients." (PMID 33243159, 2020). "Although some people at highest risk of death may be identified by the diagnosis of an obvious opportunistic infection or awareness of a high VL, many would be missed without a CD4 test." (PMID 31141516, 2019). "However, measurement of CD4 count remains an important metric for identifying patients with advanced HIV disease, and assessing a person’s overall immune status, which informs the decision to offer opportunistic infection screening and prophylaxis." (PMID 30794637, 2019). "Such statistical differences between median CD4 counts in CMCs versus UMCs may not be clinically meaningful as very limited opportunistic infections or comorbidities may develop at a difference of 33 CD4 cells/μl)." (PMID 29412520, 2018). "Patients who start ART at the baseline CD4 counts <200 cells/μl have frequently been demonstrated to have a subsequent poor immune recovery on receipt of ART, taking a much long time before gaining an adequate immunity against most opportunistic infections (OIs) including TB." (PMID 30073038, 2018). "Similar to other reports, low CD4+ counts in this study predicted UTI among HIV-infected pregnant women, an observation that could be explained by the severity of immunosuppression and the increased likelihood for opportunistic infections, including UTI." (PMID 28255302, 2017). "Nevertheless, it is important to note that recurrent malaria infection in non-ART patients may deplete their CD4 count to such a level that could expose them to potential opportunistic infections and warrant early commencement of ART." (PMID 28346490, 2017). "Indeed, CD4+ cell count is still a key factor in determining the stage of HIV infection and plays a role in guiding clinical care to start or discontinue the prophylaxis for opportunistic infections." (PMID 28166729, 2017). "Considering the very low CD4 count, and absence of other opportunistic infections in our case suggests that CL could be a potential opportunistic infection in HIV." (PMID 28841834, 2017). "Although virus load testing is anticipated to eclipse CD4 counts in long-term monitoring, at present CD4 testing at POC with rapid turn-around time informs opportunistic infections prophylaxis, ART management and may guide switching to second line therapy or prompt targeted virus load testing." (PMID 27388763, 2016). "Despite the fact that every PLE patient studied has had very low CD4 counts, no opportunistic infections have been found – as may be expected with CD4 lymphopenia." (PMID 27277425, 2016).